NLRP3 (NLR family pyrin domain containing 3)
Diseases named in the same sentence as NLRP3 in open-access papers (continued):
Sharing a sentence is not in itself a finding about the gene and the disease.
Obesity (continued). "We studied this in the context of aging and obesity due to our prior work linking NLRP3 inflammasome activation to metabolic inflammation in these conditions and our subsequent discovery that BHB inhibits the NLRP3 inflammasome." (PMID 36775129, 2023). "Studies in mice show that deletion of Nlrp3 protects against HFD-induced obesity, IR, dyslipidemia as well as infiltration of macrophages into the AT, and leads to improved serum glucose and insulin levels and insulin signaling in liver and cardiac tissue." (PMID 37239938, 2023). "The signature of ApoE involved in inflammation and lipid metabolism is found both in mice and humans across multiple obesity models, suggesting the pluripotent role of ApoE in the NLRP3-mediated inflammation induced by obesity." (PMID 38062308, 2023). "The NLRP3 inflammasome activation can be prevented by reducing caloric intake and represents another mechanistic link between obesity, IR and T2DM." (PMID 37627482, 2023). "In a study on mice with obesity and asthma, vitamin D3 levels were related to the increased expression of IL-1β mRNA and NLRP3 mRNA in lung tissue." (PMID 38276294, 2023). "In particular, NLRP3 inflammasome is activated by cellular stress response and obesity-induced inflammatory response in adipocytes and promotes the autoactivation of Cas-1, which induces the activations of mediators of immune response." (PMID 37334306, 2023). "NLRP3 inflammasome is activated by ceramides sensing, inducing IL-1β production through caspase-1 activation, contributing to obesity-induced inflammation and insulin resistance." (PMID 37819510, 2023). "A recent study investigated the impact of metabolic dysfunctions on NLRP3 inflammasome activation in the context of obesity." (PMID 38068904, 2023). "The role of NLRP3 inflammasome in the pathogenesis of obesity was supported by data showing that the genetic deletion of Nlrp3 and Asc in high-fat diet fed mice results in improved glucose tolerance and IR." (PMID 37627482, 2023). "Strong evidence indicates that the NLRP3 inflammasome plays a crucial role in obesity-induced inflammation and IR." (PMID 37446154, 2023). "Additionally, some of the protective effects of the NLRP3 inflammasome may also be mediated via IL-18, as deficiency of Il18 in diabetes-prone non-obese diabetic mice induces the spontaneous development of obesity, hyperglycemia and IR, which can be reversed by IL-18 administration." (PMID 37239938, 2023). "In line with this, cholesterol crystals and palmitate (the most increased serum fatty acid in obesity) have also been categorized as sterile inflammation instigators through NLRP3 inflammasome activation." (PMID 37819510, 2023). "MUFA can inhibit adipose (NLRP3) inflammasome-mediated IL-1β secretion, NLRP3 secretion, and insulin resistance, even in mice with diet-induced obesity." (PMID 37175603, 2023). "In summary, our data demonstrated that ApoE ablation alleviates obesity and dysregulation of glucose metabolism at the expense of inciting chronic inflammation through NLRP3 inflammasome in obesity." (PMID 38062308, 2023). "Persistent low-grade inflammation is believed to underlie many diseases of aging and we have previously shown that the NLRP3 inflammasome is a key driver of age-related and obesity-driven inflammation." (PMID 36775129, 2023). "Studies have reported that obesity can induce the formation of the NLRP3 inflammasome, sustaining the inflammatory environment often noticed in AT in obesity." (PMID 37035745, 2023). "Conversely, PQQ decreased NLRP3 inflammasome and caspase 1 expression, suggesting that PQQ managed mitochondrial dysfunction and low-grade inflammation caused by obesity by improving mitochondrial biogenesis." (PMID 37214340, 2023). "A growing number of studies have demonstrated the association of NLRP3 and PFAS in gastric cells and rodent models of obesity and lung development." (PMID 37239886, 2023).
Obesity (continued). "Raut and coworkers also demonstrated that adiponectin, an adipokine severely diminished in obesity that exerts anti-inflammatory and antitumor actions, completely suppressed leptin-induced NLRP3 inflammasome activation." (PMID 37819510, 2023). "Obesity also promotes the assembly of the NLRP3 inflammasome in macrophages, which induces macrophage‐mediated T cell activation and IFN‐γ release." (PMID 37125240, 2023). "In the obesity context, where the NLRP3 inflammasome confers detrimental effects, HFD and WD were used in almost all studies." (PMID 37239938, 2023). "NLRP3 inflammasome activation is a key phenotypic feature of obesity-related asthma, and NLRP3 gene expression in the sputum of patients with obesity-related asthma is significantly increased and correlated with BMI." (PMID 38029078, 2023). "Recent findings suggest a different role of the inflammasome NLRP3 among the various obesity classes." (PMID 36012889, 2022). "Evidence comes from the increased expression of NLRP3 in adipose tissue (AT) from humans and mouse models with obesity and from the demonstrated role of NLRP3 as an important regulator of adipocyte differentiation." (PMID 35931812, 2022). "By reducing NLRP3 inflammasome activity, HFCD plus high fructose-fed mice exhibited significantly improved obesity-associated metabolic abnormalities." (PMID 35563780, 2022). "In this review, we discuss the new findings on how obesity induces macrophage mitochondrial dysfunction and how mitochondrial dysfunction induces NLRP3 inflammasome activation." (PMID 36012516, 2022). "The activation of NLRP3 inflammasome were reported to relating with a wide range of diseases, such as type 2 diabetes, Alzheimer’s disease, obesity, cerebral and myocardial ischemic diseases, and a variety of auto-immune and auto-inflammatory diseases." (PMID 36386225, 2022). "In conclusion, targeting autophagy and NLRP3 inflammasome as therapeutic strategies is beneficial in managing AT inflammation and obesity-related complications." (PMID 35432210, 2022). "Increased miR-451 caused by obesity, decreased AMPKα expression and sequentially increased NADPH oxidase activity were responsible for the activation of NLRP3." (PMID 35915511, 2022). "Dysregulation of lipid metabolism triggers NLRP3 activation leading to obesity-induced inflammation and insulin resistance." (PMID 36310177, 2022). "A number of studies have demonstrated that metabolic dysregulation, such as obesity, leads to the activation of the NLRP3 inflammasome in various cells, including PBMCs and endothelial cells." (PMID 35563363, 2022). "Identification of the role of NLRP3 raised another important question: which cell population is responsible for NLRP3 expression and functionality in the obesity setting?" (PMID 35915511, 2022). "A study investigating the role of NLRP3 inflammasome in obesity and obesity-induced inflammation shows that the mRNA levels of IL-1β and NLRP3 in the visceral adipose tissue are positively correlated with BW of C57BL/6 mice." (PMID 36142842, 2022). "The last ones initiate inflammatory responses by detecting pathogen- or danger-associated molecular patterns by pattern-recognition receptors such as NLRP3, which plays a key role in the obesity-specific chronic inflammation and progression of IR." (PMID 36558167, 2022). "Using gain- and loss-of-function approaches, we found that SCs were the cell population responsible for NLRP3 expression and functionality in the obesity setting." (PMID 35915511, 2022). "In view of the recently revealed presence of bacteria and bacterial DNA in AT in obesity, it therefore appears feasible that the required ‘first signal’ for NLRP3 inflammasome activation is provided to ATM in obesity." (PMID 35931812, 2022). "Obesity-related inflammasome activation in AT and liver was prevented, and insulin signaling was improved in Nlrp3- mice." (PMID 35432210, 2022).
Obesity (continued). "The adipose tissue NLRP3 inflammasome has recently emerged as a contributor to obesity-related metabolic inflammation." (PMID 36065376, 2022). "There has been increasing recognition that NLRP3 inflammasome activation acts as a chief instigator of obesity, contributing to obesity-related systemic inflammation and insulin resistance." (PMID 36483560, 2022). "Researchers have demonstrated that reduction of NLRP3 expression in adipose tissue prevented the obesity-induced inflammasome activation in liver and improved insulin sensitivity in obese type-2 diabetic patients." (PMID 35563780, 2022). "HO-1 has been shown to reduce NLRP3 inflammasome activity in mice; it also reduces visceral fat accumulation, normalizes metabolic profiles, and prevents obesity, thereby reducing cardiovascular and renal complications." (PMID 35784553, 2022). "The NLRP3 inflammasome is critical in metabolic dysregulation and control of obesity-related IR and pancreatic β-cell dysfunction." (PMID 35844498, 2022). "Growing evidence indicates that the innate immune response pathway from the NLRP3 inflammasome, to interleukin-1 to interleukin-6, is involved in the generation of obesity-related systemic inflammation and heart failure with preserved ejection fraction." (PMID 36483560, 2022). "Previous studies have demonstrated that the infiltration of macrophages into adipose tissue is the primary source of NLRP3 inflammasome activation in obesity." (PMID 36065376, 2022). "Lipotoxic ceramide and saturated FA palmitate, which are both elevated in obesity, can activate the NLRP3 inflammasome through autophagy inhibition and accumulation of mtROS." (PMID 36012516, 2022). "In summary, we have shown that macrophages from people with obesity, and whole tissue cultures from visceral AT, show increased [Ca2+]ex-induced, CaSR-mediated NLRP3 inflammasome activation and IL-1ß release when compared to people who were not obese." (PMID 35931812, 2022). "The unique expression pattern of NLRP3 in the testes of obese mice implied a distinct role for NLRP3 during the development of obesity-related spermatogenesis impairment." (PMID 35915511, 2022). "Inhibition of the NLRP3 inflammasome reduces obesity-induced macrophage activation and thereby reduces inflammation." (PMID 36142890, 2022). "During obesity, macrophages in adipose tissue express high levels of NLRP3 and release inflammatory cytokines such as TNF-α and IL-1β." (PMID 35844498, 2022). "Based on the in vivo and in vitro data, we concluded that SCs NLRP3 contributes to the development of obesity-related spermatogenesis impairment." (PMID 35915511, 2022). "There is a two-way link between NLRP3 inflammation and obesity: the metabolic imbalances related to obesity activate inflammation and, once activated, inflammation influences the prognosis." (PMID 35055149, 2022). "Various studies have revealed the role of the NLR family pyrin domain-containing 3 (NLRP3) inflammasome in the development of adipocyte dysfunction, inflammation, oxidative stress, and insulin resistance in obesity." (PMID 36033946, 2022). "Here, we focus on the mutual regulation and cellular mechanism between NLRP3 inflammasome and autophagy in AT during obesity." (PMID 35432210, 2022). "In the current context of SARS-COV2 infections, the connection between obesity and NLRP3 activation seems to play an important role in the outcome of COVID-19 in these patients." (PMID 35055149, 2022). "Suppression of the NLRP3 -IL-1β pathway has been reported in the amelioration of obesity by preventing adipose tissue expansion and inflammation in various murine models." (PMID 36033946, 2022). "Accumulating evidence indicates that adipose tissue of obese subjects has higher NLRP3 compartments and IL-1β expression compared to that of lean individuals, showing positive correlation between NLRP3 signaling in adipose tissue and obesity." (PMID 36142842, 2022).
Obesity (continued). "Among the DAMPs, saturated fatty acids and other dietary metabolites derived from chronic nutrient excess have a key role in regulating NLRP3 activation in obesity, promoting insulin resistance and metabolic alterations." (PMID 35806353, 2022). "NLRP3 or ASC knockout abolished obesity, insulin resistance, hepatic steatosis, and contractile dysfunction but did not prevent cardiac hypertrophy." (PMID 36320147, 2022). "T2DM is an obesity-related metabolic syndrome with the sustained activation of the NLRP3 inflammasome, which is a critical component of the innate immune system mediating caspase-1 activation and the secretion of proinflammatory cytokines IL-1β/IL-18." (PMID 36558167, 2022). "In our future study, we will use macrophage conditional knockout mice to investigate the role of macrophage-derived NLRP3 in obesity-related spermatogenesis impairment." (PMID 35915511, 2022). "Over the last years, compelling evidence has been accumulated showing the involvement of the NLR family pyrin domain containing 3 (NLRP3) inflammasome in the development of diet-induced obesity, insulin resistance and type 2 diabetes." (PMID 35931812, 2022). "Ablation of NLR family pyrin domain containing 3 (NLRP3) inflammasomes in obesity reduced inflammation and adipose tissue IFN-γ and improved insulin sensitivity." (PMID 36552805, 2022). "NLRP3 has been widely described in obesity, and it is upregulated in the subcutaneous and visceral adipose tissue from patients with obesity." (PMID 35158762, 2022). "Our findings indicate that EMPA improves obesity-related kidney disease through reduction of NLRP3 inflammasome activity and upregulation of the HO-1–adiponectin axis, suggesting a novel mechanism for SGLT2i-mediated renal protection in obesity." (PMID 35784553, 2022). "Relatedly, obesity-associated danger signals, such as free fatty acid, can be sensed by the NLRP3 inflammasome in both animals and humans to exacerbate obesity-induced inflammation and insulin resistance." (PMID 35216355, 2022). "It should be noted that NLRP3 inflammasome-derived IL-1β plays an important role in the obesity model: this cytokine is upregulated in obesity, and blockade of IL-1β abolishes obesity-induced ILC3-mediated AHR." (PMID 36466877, 2022). "The role of NLRP3 inflammasome and NF-κB in mediating adipocyte dysfunction, inflammation, oxidative stress, and insulin resistance in obesity have been reported in previous studies." (PMID 36033946, 2022). "In light of this evidence, tranilast is under evaluation as a treatment for patients with COVID-19 whose lung damage appears to be promoted by obesity through an NLRP3-driven mechanism." (PMID 35806353, 2022). "NLRP3 activation in obesity has been described to occur in adipocytes, but also in adipose tissue macrophages (ATM)." (PMID 35931812, 2022). "There are interactions about altered autophagy and NLRP3 inflammasome activation during the progress in obesity." (PMID 35432210, 2022). "Among the consequences of NLRP3 inflammasome activation is systemic chronic low-grade inflammation, a cardinal feature of obesity and insulin resistance." (PMID 33435142, 2021). "The aim of our study was to characterize the levels of NOD-like receptor protein 3 (NLRP3) inflammasome activation in ovaries and liver of mice during obesity progression." (PMID 34805147, 2021). "In vivo, we demonstrated that hematopoietic APPL1 is crucial to restrict NLRP3 inflammasome activation in obesity and acute septic response." (PMID 34789781, 2021). "To assess the effects of GC-VLNs on NLRP3 inflammasome-mediated chronic inflammation in obesity, we fed C57BL/6J mice with a high-fat diet (HFD) for 15 weeks to induce obesity and obesity-associated chronic inflammation." (PMID 34646372, 2021). "Nonetheless, the regulation of ovarian inflammation in late obesity (16- week HFD) seems to be independent from NLRP3 inflammasome activation, as IL-18 and CASP1 mature proteins were significantly downregulated." (PMID 34805147, 2021).
Obesity (continued). "More recently, the possible involvement of NOD-, LRR- and pyrin domain-containing protein-3 (NLRP3) inflammasome in obesity has also been articulated." (PMID 34684569, 2021). "In summary, our work evidences the major role of leptin signaling on NLRP3 inflammasome activation in the ovary of mice during early obesity." (PMID 34805147, 2021). "Palmitate-induced NLRP3 inflammasome complex formation disrupts endothelial tight junctions, leading to the onset of endothelial injury during obesity." (PMID 33546399, 2021). "The activation of NLRP3 inflammasome by over-nutrition is involved in chronic sterile inflammation, which is a critical immune process in obesity." (PMID 34107901, 2021). "This obesity-mediated inflammation through NLRP3 inflammasome results in a further deterioration of metabolic control leading to metabolic disorders such as non-alcoholic fatty liver disease (NAFLD)." (PMID 33435142, 2021). "We also present the available experimental evidence linking NLRP3 inflammasome activation with obesity in the skeletal muscle." (PMID 33806797, 2021). "Since patients with obesity have an increased expression of the inflammasome component NLRP3, infection with SARS-CoV-2 probably leads to an exaggerated pyroptotic response in patients with obesity, with features of macrophage activation syndrome." (PMID 33512658, 2021). "Our results evidencing NLRP3 inflammasome activation in the ovaries in early obesity (after 4- week HFD) are in line with previous reports showing the accumulation of proinflammatory mediators in the ovary of mice after short-term (6- week HFD) DIO." (PMID 34805147, 2021). "HFD-induced obesity can impair autophagy in cardiomyocytes, while the inhibition of NLRP3-inflammasome and promotion of autophagy can improve HFD-induced cardiac injury." (PMID 33796528, 2021). "Research on the modulation of the NLRP3 inflammasome via diet and fatty acid-induced obesity will open new avenues for treating or relieving complications in metabolic inflammatory disorders." (PMID 33435142, 2021). "In the present study, we explored the effect of exercise training and METRNL on NLRP3 inflammasome activation in adipose tissues to identify a potential target for the treatment of obesity-induced metabolic disorders." (PMID 34943988, 2021). "Activation of the inflammasome complex, particularly NLRP3, has a crucial role in obesity-induced inflammation, insulin resistance, and T2DM." (PMID 34070553, 2021). "We showed the link between leptin signaling and NLRP3 inflammasome activation in the ovary throughout obesity progression in mice, elucidating the molecular mechanisms underpinning ovarian failure in maternal obesity." (PMID 34805147, 2021). "The involvement of NLRP3 inflammasome in obesity pathogenesis is supported by the results demonstrating that Asc−/− and Nlrp3−/− mice were protected against HFD-induced IR and obesity." (PMID 34107901, 2021). "After garlic chive-derived VLNs (GC-VLNs) were found to exhibit potent anti-NLRP3 inflammasome activity in cell culture, such function was further assessed in a murine acute liver injury disease model, as well as in diet-induced obesity." (PMID 34646372, 2021). "NLRP3 has been reported to have a role in protecting against high fat diet-induced obesity and insulin resistance." (PMID 34585119, 2021). "In obesity, the level of circulating LPS, which acts as the priming signal for the NLRP3 inflammasome, from gut microbiota is significantly enhanced." (PMID 33535473, 2021). "This narrative review focuses on NLRP3 inflammasome activation as the mediator of systemic inflammation in obesity and metabolic disorder and factors that regulate this activation in adipose tissue." (PMID 33435142, 2021). "TNF-α, a multifunctional adipokine that is increased in obesity, is a potent endogenous NLRP3 inflammasome priming signal driving age-related inflammation." (PMID 33435142, 2021).